EGFR (epidermal growth factor receptor)
Diseases named in the same sentence as EGFR in open-access papers (continued):
Sharing a sentence is not in itself a finding about the gene and the disease.
head and neck squamous cell carcinoma (continued). "Fluorescence molecular imaging using ABY-029, an epidermal growth factor receptor (EGFR)-targeted, synthetic Affibody peptide labeled with a near-infrared fluorophore, is under investigation for surgical guidance during head and neck squamous cell carcinoma (HNSCC) resection." (PMID 36875185, 2023). "EGFR, a receptor tyrosine kinase also known as common upstream kinase of both Akt and ERK signalings, plays key roles in cell growth and differentiation pathways in head and neck squamous cell carcinoma (HNSCC)." (PMID 36376983, 2022). "Long intergenic non-protein coding RNA 52 (LINC00052) promotes head and neck squamous cell carcinoma (HNSCC) progression through the regulation of EGFR by sponging miR-608." (PMID 35999564, 2022). "The first antibody-photosensitizer conjugate (APC) of world is RM-1929, an antibody cetuximab targeting epidermal growth factor receptor (EGFR)-conjugated PS IR700, was approved for marketing in Japan in September 2020 for the treatment of head and neck squamous cell carcinoma." (PMID 36212416, 2022). "Honokiol, isolated from the bark, seed cones and leaves of the trees of the genus Magnolia, could inhibit EGFR in head and neck squamous cell carcinoma (HNSCC) cells, resulting in reduced activities of its downstream proliferative and survival targets, such as AKT, STAT3, BCL-XL and cyclin D1." (PMID 35269825, 2022). "Glycoproteins such as EGFR, E-cadherin, CD44, PD-1/PD-L1, B7-H3 and Muc1 play important roles in the progression of head and neck squamous cell carcinoma (HNSCC), and their levels of glycosylation and changes in glycosyl structure are closely linked to HNSCC progression and malignant transformation." (PMID 33531990, 2021). "Treatment of head and neck squamous cell carcinoma (HNSCC) requires combined modalities of surgery, radiation and cytotoxic chemotherapy as well as targeted anti-epidermal growth factor receptor (EGFR) agents and most recently, immunotherapies that inhibit the PD1-PD-L1 axis." (PMID 33485341, 2021). "It was reported that ANO1 forms a direct complex with EGFR through the trans/juxtamembrane domain of EGFR in head and neck squamous cell carcinoma (HNSCC) cells; knockdown of ANO1 resulted in greatly reduced EGFR protein levels, which functionally translated to decreased cell proliferation." (PMID 33250781, 2020). "In addition to EGFR, the rate of Smads mutations is also low in OSCC tissues, although current evidence suggests that the deletion of Smad4 contributes to the metastasis of head and neck squamous cell carcinoma (HNSCC)." (PMID 30914776, 2019). "Interestingly, the epidermal growth factor receptor (EGFR, HER1) plays an integral role in the tumorigenesis and is richly expressed in a wide range of malignancies, including head and neck squamous cell carcinoma (HNSCC)." (PMID 29603584, 2018). "Two clinical trials uncovered that afatinib achieved better clinical improvements than erlotinib in lung squamous cell carcinoma (LUSC) or methotrexate in head and neck squamous cell carcinoma (HNSCC), illustrating afatinib’s outstanding clinical efficacy in tumors with wild-type EGFR." (PMID 30157900, 2018). "In addition to reducing membrane expression of EGFR, HSP90 inhibition significantly prevented tumor growth in head and neck squamous cell carcinoma animal models." (PMID 29777377, 2018). "Resistance to epidermal growth factor receptor (EGFR)-targeted therapy is insufficiently understood in head and neck squamous cell carcinoma (HNSCC), entailing the lack of predictive biomarkers." (PMID 27119512, 2016). "Cetuximab is an anti-EGFR antibody that has been shown to improve survival when combined with RT in patients with loco-regionally advanced non-NPC head and neck squamous cell carcinoma (HNSCC)." (PMID 29147412, 2015).
head and neck squamous cell carcinoma (continued). "Aberrant activation of signaling pathways downstream of epidermal growth factor receptor (EGFR) has been hypothesized to be one of the mechanisms of cetuximab (a monoclonal antibody against EGFR) resistance in head and neck squamous cell carcinoma (HNSCC)." (PMID 22549044, 2012). "However, the relationship between EMT and resistance to an epidermal growth factor receptor (EGFR) -targeting drug in head and neck squamous cell carcinoma (HNSCC) remains unknown." (PMID 22315058, 2012). "Amplification and overexpression of EGFR gene may play roles in the invasion and progression in cancer, and the elevated expression may be an indicator for tumor recurrence and lower survival in head and neck squamous cell carcinoma (HNSCC)." (PMID 22920630, 2012). "Even though head and neck squamous cell carcinoma (HNSCC) is the seventh most common cancer worldwide, there are only two PD-1 targeted immunotherapies (pembrolizumab and nivolumab) and one tumor intrinsic EGFR targeted therapy (cetuximab) that are FDA approved for treatment of HNSCC." (PMID 40473660, 2025). "However, in clinical practice, it is considered sufficient to treat head and neck squamous cell carcinoma without confirming the intensity of EGFR expression, as EGFR is highly expressed in head and neck squamous cell carcinoma." (PMID 39735016, 2024). "In head and neck squamous cell carcinoma (HNSCC), the oxidative stress induced by HO∙ modifies the expression of BRAK and IL-8 genes in human HNSCC cells via the EGFR/MEK/ERK pathway, thereby promoting angiogenesis and facilitating tumor progression." (PMID 37469162, 2024). "In 2006, cetuximab, a chimeric monoclonal antibody against EGFR, was announced by the United States Food and Drug Administration (the FDA) to be approved for use in HNSCC (Head and Neck Squamous Cell Carcinoma) patients." (PMID 38784388, 2024). "Nanobody-based EGFR-targeted PDT was further explored in patient-derived organoids from a head and neck squamous cell carcinoma (HNSCC), showing superior efficacy compared to antibody-targeted PDT." (PMID 38067344, 2023). "A groundbreaking report confirmed that high expression of CAF-specific VEGFA, PGE2S, COX2, EGFR, CCL2, and NANOG was considered as the culprit of CDDP resistance development in head and neck squamous cell carcinoma (HNSCC)." (PMID 36359776, 2022). "Accordingly, we subjected head and neck squamous cell carcinoma (HNSCC) and TNBC cells for treatment with SSTNEGFR to probe the involvement of Sdc4 as a partner in EGFR signaling in these cancers." (PMID 35569509, 2022). "In view of the clinical translation, the Nb-based EGFR-targeted PDT in a 3D head and neck squamous cell carcinoma (HNSCC)-patient-derived model was also investigated." (PMID 35213974, 2022). "For instance, the epidermal growth factor receptor (EGFR) is found to be overexpressed in head and neck squamous cell carcinomas (HNSCC), mostly in HPV-negative cases." (PMID 36558861, 2022). "Epidermal growth factor receptor (HER1) overexpression is a frequent molecular alteration in head and neck squamous cell carcinoma (HNSCC) and its increased expression and activity have been associated with worse clinical outcome and resistance to RT." (PMID 35761298, 2022).
head and neck squamous cell carcinoma (continued). "In head and neck squamous cell carcinoma (HNSCC), HOXB5 functions as an oncogene, which binds directly to the promoter region of EGFR and regulates the AKT/Wnt/β-catenin synergistic signaling axis to enhance proliferation, cell migration, invasion, and EMT." (PMID 34617205, 2022). "The discovery of the role of epidermal growth factor receptor (EGFR) overexpression in the pathogenesis of HNC has opened new pathways in the development of novel therapeutic agents for the targeted treatment of recurrent and/or metastatic head and neck squamous cell carcinoma." (PMID 34638405, 2021). "In addition, head and neck squamous cell carcinoma (HNSCC) and the human papillomavirus (HPV) therapy with HER receptors, anti-EGFR therapies have shown that afatinib monotherapy or afatinib combined with carboplatin can increase the sensitivity of cetuximab‐resistant cells." (PMID 34976824, 2021). "The epidermal growth factor receptor (EGFR) is a therapeutic target in head and neck squamous cell carcinoma (HNSCC)." (PMID 34568028, 2021). "The epidermal growth factor receptor (EGFR) inhibitor cetuximab is the only FDA-approved oncogene-targeting therapy for head and neck squamous cell carcinoma (HNSCC)." (PMID 34546978, 2021). "Radiotherapy (RT) plus the anti‐EGFR monoclonal antibody Cetuximab (CTX) is an effective combination therapy for a subset of head and neck squamous cell carcinoma (HNSCC) patients." (PMID 34062049, 2021). "Epidermal growth factor receptor (EGFR) is often overexpressed in head and neck squamous cell carcinoma (HNSCC) and represents a top candidate for targeted HNSCC therapy." (PMID 33540470, 2021). "In head and neck squamous cell carcinoma (HNSCC) cells, EGF has been shown to function as an upstream factor of CXCL14, and the EGFR tyrosine kinase inhibitor can restore CXCL14." (PMID 34696665, 2021). "It is reported that in head and neck squamous cell carcinoma (HNSCC) cells, the NGF/TrkA axis confers resistance to the EGFR inhibitor Erlotinib through the EMT process." (PMID 34568317, 2021). "Epidermal growth factor receptor (EGFR) is a target for the therapeutic antibody cetuximab (CTX) in head and neck squamous cell carcinoma (HNSCC)." (PMID 35008337, 2021). "Epidermal growth factor receptor (EGFR) is highly expressed in head and neck squamous cell carcinoma (HNSCC) and correlates with poor prognosis." (PMID 31823521, 2020). "The epidermal growth factor receptor inhibitor cetuximab is the only oncogene-targeted agent that has been FDA approved for the treatment of head and neck squamous cell carcinoma (HNSCC)." (PMID 31914141, 2020). "We screened 19 anticancer compounds, targeting the epidermal growth factor receptor (EGFR), MEK, and PI3K/mTOR on 12 head and neck squamous cell carcinoma (HNSCC) cell lines cultured on plastic, mouse sarcoma–derived Matrigel (MSDM), and Myogel." (PMID 31905951, 2019). "This manuscript contributes a new comprehension of the molecular heterogeneity of head and neck squamous cell carcinoma (HNSCC) and finds a way of potentially exploiting this heterogeneity through the demonstration that one subgroup (basal) is particularly sensitive to the EGFR blockade." (PMID 31181806, 2019). "The overexpression of Epidermal Growth Factor Receptor (EGFR) in >90% of head and neck squamous cell carcinoma (HNSCC) lesions correlates with adverse prognosis, and was used as a rationale to evaluate the effect of EGFR-targeted therapies." (PMID 31640284, 2019). "Acquired resistance to cetuximab (CTX), a monoclonal antibody that can block the binding of EGF to EGFR and inhibit the activation of downstream pathways AKT and ERK1/2, was found in head and neck squamous cell carcinomas (HNSCC)." (PMID 30927928, 2019). "Epidermal growth factor receptor (EGFR) targeted therapies have shown limited efficacy in head and neck squamous cell carcinoma (HNSCC) patients despite its overexpression." (PMID 31827134, 2019).
head and neck squamous cell carcinoma (continued). "The epidermal growth factor receptor (EGFR, HER1) is a therapeutic target in head and neck squamous cell carcinoma (HNSCC)." (PMID 29603584, 2018). "Cetuximab, a monoclonal antibody against EGFR, is FDA approved for the treatment of metastatic colorectal cancer and head and neck squamous cell carcinoma (HNSCC)." (PMID 29792227, 2018). "However, cetuximab improves the efficacy of radiotherapy in only a subgroup of patients with head and neck squamous cell carcinoma (HNSCC), with 50% of patient still experiencing local recurrence, and EGFR levels cannot predict the efficacy of cetuximab combined with radiotherapy." (PMID 29232380, 2017). "Evidence reported that small molecule EGFR-TKI targeting EGFR can increase autophagy in head and neck squamous cell carcinoma (HNSCC) cells, ovarian cells, and bladder cancer cells." (PMID 28531218, 2017). "Epidermal growth factor receptor (EGFR) is overexpressed in up to 90% of head and neck squamous cell carcinoma (HNSCC) tumors." (PMID 28881811, 2017). "In line with results concerning other EGFR-targeted TKIs in NSCLC, erlotinib also elicits cytotoxicity via oxidative stress generation in head and neck squamous cell carcinoma (HNSCC) cell lines, again being reversible with N-acetyl cysteine." (PMID 28698765, 2017). "Stimulation of the EGFR pathway with EGF or TGF-α induced PIM-1 upregulation and nuclear translocation in head and neck squamous cell carcinoma (HNSCC) cell lines." (PMID 27596051, 2016). "The epidermal growth factor receptor (EGFR) is frequently overexpressed in head and neck squamous cell carcinoma (HNSCC) and several other human cancers." (PMID 27716204, 2016). "We investigated the effects of cetuximab (EGFR antibody) and IMC-A12 (IGF-1R antibody) on the response of head and neck squamous cell carcinoma (HNSCC) to radiation therapy (RT)." (PMID 25355701, 2015). "In a trial where 92 treatment-naïve patients with advanced head and neck squamous cell carcinoma received standard therapy either with or without nimotuzumab, EGFR expression showed a significant correlation with patient survival in patients treated with nimotuzumab and chemoradiation." (PMID 25918252, 2015). "Epidermal growth factor receptor (EGFR) and VEGFR are strongly expressed in head and neck squamous cell carcinomas (HNSCC), including NPC." (PMID 26418895, 2015). "Cross-talk between the two at the receptor level contributes to HNSCC (head and neck squamous cell carcinoma) via triggering EGFR/ErbB signaling by a GPCR ligand." (PMID 25599599, 2015). "Targeted therapy against the Epidermal Growth Factor Receptor (EGFR) is among the most promising molecular therapeutics for Head and Neck Squamous Cell Carcinoma (HNSCC)." (PMID 24899223, 2014). "In this study, we discovered that EGFR inhibition although increased MHC-II expression, paradoxically it attenuated HTL responses against some head and neck squamous cell carcinoma (HNSCC) cells." (PMID 25240937, 2014). "Our previous work demonstrated that small molecule EGFR inhibitors including erlotinib decreased VEGF mRNA expression, decreased secretion of VEGF protein, and blunted HIF-1α induction in response to hypoxia in SQ20B head and neck squamous cell carcinoma cells." (PMID 19657384, 2009). "In addition, TAVO412 also demonstrated activities in tumor types with dysregulated EGFR, c-Met, and VEGF signaling, such as head and neck squamous cell carcinoma (HNSCC), ovarian cancer (OC), hepatocellular carcinoma (HCC), and small cell lung cancer (SCLC)." (PMID 39995668, 2025). "Here, we evaluated synergistic antitumor efficacy of EGFR × MET targeting bispecific antibody, amivantamab with PD-L1 immunotherapy, pembrolizumab in head and neck squamous cell carcinoma (HNSCC) and lung squamous cell carcinoma tumor–bearing humanized patient-derived xenograft (PDX) models." (PMID 38916448, 2024).
head and neck squamous cell carcinoma (continued). "In recent years, the use of anti-EGFR mAbs has played an increasing role in the treatment of several solid tumour types including non-small-cell lung carcinoma (NSCLC), colorectal cancer (CRC), and head and neck squamous cell carcinoma (HNSCC) in which KRAS mutation is not detected." (PMID 35814459, 2022). "It has been shown that head and neck squamous cell carcinoma (HNSCC) cells expressing CD44v are intrinsically resistant to EGFR-TKIs due to xCT-dependent cystine transport, whereas differentiated HNSCC cells are CD44v-negative and EGFR-TKIs sensitive." (PMID 36338517, 2022). "Activation of epidermal growth factor receptor (EGFR) pathways and MEK/ERK signalling lead to c-Jun mediated Axl mRNA expression in non-small cell lung cancer (NSCLC) and head and neck squamous cell carcinoma (HNSCC)." (PMID 33806258, 2021). "Epidermal growth factor receptor (EGFR) inhibitors have limited efficacy in head and neck squamous cell carcinoma (HNSCC) due to various resistance mechanisms, such as activation of the insulin-like growth factor-1 receptor (IGF1R), which initiates pro-survival signaling." (PMID 30729097, 2019). "Epidermal growth factor receptor (EGFR) tyrosine kinase inhibitors (TKIs) have not been effective in unselected head and neck squamous cell carcinoma (HNSCC) populations." (PMID 27004400, 2016). "On the other hand, EGFR could enhance COX-2 expression in normal and tumor cells such as head and neck squamous cell carcinoma (HNSCC) cell line mainly through Ras/Raf/MAPK." (PMID 27923354, 2016). "Epidermal growth factor receptor (EGFR) is an important molecular target for antineoplastic therapy in head and neck squamous cell carcinoma (HNSCC) as it is found to be upregulated and overexpressed in the majority of HNSCCs and is associated with a poor clinical prognosis." (PMID 27738319, 2016). "We tested our hypotheses in three human head and neck squamous cell carcinoma (HNSCC) cell lines, HN5, FaDu, and UMSCC1, which express different levels of EGFR and respond to cetuximab differentially." (PMID 25871473, 2015). "Epidermal growth factor receptor (EGFR) inhibitors are approved by the Food and Drug Administration (FDA) but remain under active clinical investigation for the treatment of both newly diagnosed and recurrent/metastatic head and neck squamous cell carcinoma (HNSCC)." (PMID 35158773, 2022). "The goal of this study is to study the synergy of anti-HER2, trastuzumab, and anti-EGFR, cetuximab, and characterize the tumor microenvironment components that may lead to increased radiation sensitivity with dual anti-HER2/EGFR therapy in head and neck squamous cell carcinoma (HNSCC)." (PMID 38355949, 2024). "However, in head and neck squamous cell carcinoma (HNSCC), despite the high expression of epidermal growth factor receptor (EGFR), RTKI treatment often fails to show therapeutic efficacy in clinical trials, questioning their inclusion in standard therapy regimens." (PMID 38263982, 2023). "However, the correlation between EGFR and ERS signaling pathways in head and neck squamous cell carcinoma has not been well studied." (PMID 30414263, 2018).